DICER1 (dicer 1, ribonuclease III)
Diseases named in the same sentence as DICER1 in open-access papers (continued):
Sharing a sentence is not in itself a finding about the gene and the disease.
breast carcinoma (55 papers, 2007 to 2025). "Another study investigated the germline mutations of DICER1 in Chinese patients with familial breast cancer." (PMID 40666073, 2025). "Consistent with previous findings in mouse models of primary breast cancer, colon cancer, and glioblastoma, we observed a tumor-protective role of Dicer1-deficient, M1-like macrophages in both the MC38 colon cancer model and an orthotopic NSCLC model." (PMID 40475851, 2025). "Let-7 and miR-29a were also reported to be higher in ERα− breast cancer cells and known to collectively target and repress Dicer1, thereby leading to a loss of differentiation and an increase in aggressive behavior similar to the TNBC subtype." (PMID 36834918, 2023). "Upregulation of TARBP2 (12q12-q13), a cytoplasmic endonuclease which cleaves pre-miRs into 21 to 22 nucleotide mature miRs in conjunction with Dicer (DICER1), has been associated with metastasis in breast cancer." (PMID 27453764, 2016). "One of these Dicer1 variants, Dicer1e, was recently found to be differentially expressed in breast cancer cells." (PMID 25115815, 2014). "One of these Dicer1 mRNA splice variants termed, Dicer1e, was predicted to translate a 93-kDa protein which was found to be differentially expressed between epithelial and mesenchymal breast cancer cells." (PMID 25115815, 2014). "We detected loss of Dicer1 in untreated mammary cancer (G2)." (PMID 32458624, 2020). "In addition, low expression levels of DICER1 mRNA were also found to be associated with a poor prognosis and relapse of many diseases, such as cervical cancer, ovarian cancer, breast cancer, and lung cancer." (PMID 29853562, 2018). "We analyzed the difference of DICER1 expression among different breast cancer subtypes based on the UALCAN database." (PMID 40666073, 2025). "In summary, through integrative multi-omics analysis and clinical validation, this study elucidated the expression patterns, molecular mechanisms, and clinical significance of DICER1 in breast cancer." (PMID 40666073, 2025). "In summary, the expression patterns, molecular mechanisms, and clinical significance of DICER1 in breast cancer have become a current research hotspot." (PMID 40666073, 2025). "DICER1 plays an important regulatory role in breast cancer, with its expression level closely related to tumor progression, the immune microenvironment, and drug sensitivity." (PMID 40666073, 2025). "Cellular experiments were conducted to verify the effects of DICER1 on the proliferation, migration, and invasion of breast cancer cells." (PMID 40666073, 2025). "The expression of DICER1 in breast cancer tissues was significantly lower than that in normal tissues, and was significantly correlated with tumor stage, T stage, and TMB levels." (PMID 40666073, 2025). "Univariate and multivariate Cox regression analyses indicated that DICER1 expression is an independent prognostic factor for breast cancer patient survival." (PMID 40666073, 2025). "CCK-8 proliferation assays demonstrated that DICER1 overexpression markedly suppressed the proliferative capacity of breast cancer cells (P < 0.05)." (PMID 40666073, 2025). "This study comprehensively investigated the expression profiles, molecular mechanisms, and clinical significance of DICER1 in breast cancer by integrating multi-omics analysis, cellular experiments, and clinical data validation." (PMID 40666073, 2025). "Total RNA was extracted from normal breast tissues and breast cancer tissues, and DICER1 expression was detected via RT-qPCR." (PMID 40666073, 2025). "By integrating genomic, transcriptomic, and epigenomic data, researchers can more comprehensively reveal the regulatory networks of DICER1 in breast cancer and its clinical significance." (PMID 40666073, 2025). "DICER1 was found to be downregulated in breast cancer tissues and closely correlated with tumor stage, tumor mutational burden (TMB) levels, and immune microenvironment features." (PMID 40666073, 2025).
breast carcinoma (continued). "This study specifically examines the RNA interference pathway regulators, particularly DICER1, to uncover its potential as a novel biomarker and therapeutic target in breast cancer." (PMID 40666073, 2025). "The expression levels of DICER1 mRNA varied among different breast cancer cell lines, with MDA-MAB-231 and HS578t showing the lowest expression of DICER1 mRNA." (PMID 40666073, 2025). "This study aims to investigate the expression patterns, molecular mechanisms, and clinical significance of DICER1 in breast cancer (BRCA), providing new biomarkers and therapeutic targets for prognosis assessment and personalized treatment of breast cancer." (PMID 40666073, 2025). "Transwell chamber assays revealed that DICER1 overexpression significantly inhibited the migration and invasion abilities of breast cancer cells (P < 0.05)." (PMID 40666073, 2025). "Future studies should further explore the mechanisms of DICER1 in breast cancer and validate its potential application value in clinical therapy." (PMID 40666073, 2025). "In clinical applications, the expression level of DICER1 has been shown to be significantly correlated with the prognosis of breast cancer patients." (PMID 40666073, 2025). "To further investigate the role of the DICER1 gene in breast cancer, we conducted drug sensitivity analysis and molecular docking analysis to explore the potential of DICER1 in predicting drug response and serving as a potential therapeutic target." (PMID 40666073, 2025). "Single-cell transcriptomic analysis revealed heterogeneous expression of DICER1 in breast cancer cell populations and its potential role in cell-cell communication." (PMID 40666073, 2025). "Alterations in the expression of DICER1 have been found in different types of cancer such as breast carcinoma, hepatocellular carcinoma, and lung cancer." (PMID 39202414, 2024). "PICK1 inhibits the processing of pre-mir-615-3p to mature miR-615-3p via interfering with the binding of DICER1 to Smad2/3 in breast cancer cells." (PMID 35183226, 2022). "For example, it has been reported that ERα directly inhibits Drosha and that Exportin 5, Dicer1, Ago1, and Ago2 are low in ERα positive breast cancers." (PMID 33477993, 2021). "It is reported that Dicer1 was involved in miR-191/425-mediated promotion of breast cancer proliferation and metastasis." (PMID 34804161, 2021). "In breast cancer, miR-191 and miR-425 are highly expressed and promote the cell proliferation and metastasis by suppressing the expression of DICER1." (PMID 34113488, 2021). "We also explored the functional coupling between activated SMAD2/3 and DICER1 to control the biogenesis of miR-615-3p in breast cancer." (PMID 32336285, 2020). "Herein, we assess the role of PICK1 on the TGF-β signaling effectors SMAD2/3 and DICER1 in the processing of pre-miR-615-3p to yield mature miR-615-3p in breast cancer cells." (PMID 32336285, 2020). "We performed several correlative and causal experiments to test if let-7b-5p, a let-7 family member, regulates DICER1 in the setting of breast cancer as well." (PMID 32204397, 2020). "APE can decrease miR-18a and MMP-9 expressions and increase Dicer1 expression in rat mammary cancer." (PMID 32458624, 2020). "In breast cancer, miR-425 is overexpressed and promotes cell growth and invasion by suppressing DICER1." (PMID 31739288, 2019). "We found that LINC00899 sponges miR-425, thereby boosting expression of DICER1 during breast cancer progression." (PMID 31739288, 2019). "DICER1 is also well known to be an important component in the oncogenic process of several cancers, such as breast cancer, hepatocellular carcinoma, lung cancer, and ovarian cancer." (PMID 31354628, 2019). "In breast cancer cells, DICER1 expression is suppressed through the inhibition of the oxygen-dependent H3K27me3 demethylases KDM6A/B, which silence the DICER1 promoter." (PMID 30459215, 2018).
breast carcinoma (continued). "However, the specific functions and mechanisms of DICER1 in breast cancer remain to be fully elucidated." (PMID 40666073, 2025). "This indicates that DICER1 may influence breast cancer progression by modulating the immune microenvironment and RNA metabolism." (PMID 40666073, 2025). "This miRNA cluster downregulates DICER1 expression by targeting the 3′untranslated region of DICER1 mRNA, thereby affecting global miRNA biogenesis and promoting the proliferation, survival, migration, and invasion of breast cancer cells." (PMID 40666073, 2025). "The expression level of DICER1 was an independent prognostic factor for breast cancer patients." (PMID 40666073, 2025). "In addition, Zhou et al25 showed that LINC00899 can significantly suppress the migration, invasion and proliferation of breast cancer cells by enhancing the expression of DICER1." (PMID 39991583, 2025). "Despite revealing the important role of DICER1 in breast cancer, this study has some limitations." (PMID 40666073, 2025). "Through integrative multi-omics analysis, cellular experiments, and clinical data validation, we have elucidated the potential mechanisms of DICER1 in breast cancer and offered novel insights for the prognostic evaluation and personalized treatment of this disease." (PMID 40666073, 2025). "DICER1 not only has the potential to become an important biomarker for prognostic evaluation of breast cancer but may also provide new insights for immunotherapy and targeted therapy." (PMID 40666073, 2025). "DICER1 has the potential to become an important biomarker for prognosis assessment in breast cancer and may provide new targets for future immunotherapy and targeted therapy." (PMID 40666073, 2025). "Moreover, the application of single-cell sequencing and spatial transcriptomics has further elucidated the heterogeneous expression of DICER1 in breast cancer cell populations and its role in immune cell communication." (PMID 40666073, 2025). "Although several novel variants were identified, no direct association between these variants and the disease was found, suggesting that DICER1 germline mutations are either rare or absent in Chinese patients with familial breast cancer." (PMID 40666073, 2025). "Through multi-omics integration and clinical validation, DICER1 not only holds promise as an important biomarker for prognostic assessment in breast cancer but may also provide new ideas for immunotherapy and targeted therapy." (PMID 40666073, 2025). "By integrating RNA-seq data, clinical data, and tumor mutation burden (TMB) data from The Cancer Genome Atlas (TCGA) database, as well as single-cell transcriptomic data from the Gene Expression Omnibus (GEO) database, we analyzed the expression characteristics of DICER1 in breast cancer." (PMID 40666073, 2025). "However, further large-scale clinical studies are needed to verify its clinical application value and to explore the potential roles of DICER1-related molecules in breast cancer treatment." (PMID 40666073, 2025). "DICER1 variants are detected in 2.38% of all cancers with non-small cell lung cancer, colorectal cancer, endometrial cancer, breast cancer, and melanoma having the greatest prevalence." (PMID 32455687, 2020). "In breast cancer, the expression of miR-18a increases, but the expression of Dicer1 decreases." (PMID 32458624, 2020). "miR-425 reportedly promotes breast cancer proliferation and metastasis by targeting DICER1." (PMID 31739288, 2019). "Further mechanistic studies revealed that LINC00899 may act as a tumor suppressor that exerts its antitumor effects by disrupting miR-425-mediated suppression of DICER1 during breast cancer development." (PMID 31739288, 2019).
breast carcinoma (continued). "We found that LINC00899 is downregulated in human breast cancer tissues and cell lines, that its overexpression suppresses cell proliferation and invasion, and that its antitumor activity during breast cancer development reflects its ability to disrupt miR-425-mediated suppression of DICER1." (PMID 31739288, 2019). "Together with results acquired above, we hypothesized that the suppressive roles of miR-129 may be attributed to the active pathway of miR-129/ESR1/Let-7b in groups of stem-like cells in breast cancer, dependent on the existence of cyclin d1/DICER1." (PMID 29262559, 2017). "It was demonstrated that miR-103/miR-107 family regulate DICER1 expression in breast cancer." (PMID 26087193, 2015). "The miR-103/miR-107 family is known to regulate DICER1 expression in breast cancer." (PMID 26087193, 2015). "Together, these data suggest that DICER1 deregulation might be involved in the etiology of human breast cancer." (PMID 17922911, 2007). "However, this hypothesis requires further investigation, particularly in the context of breast cancer, to elucidate the precise relationship between DICER1 and TMB." (PMID 40666073, 2025). "Although there is currently no direct evidence of DICER1 mutations in breast cancer, studies in other tumor types suggest that DICER1 mutations may contribute to tumor development through haploinsufficiency, which could potentially influence TMB." (PMID 40666073, 2025). "Therefore, we tested the hypothesis that miRNA-29c-3p plays a role in the observed upregulation of DICER1 in the breast cancer progression model." (PMID 32204397, 2020). "To study the mechanisms of Let-7 dysregulation in breast cancer stem-like cells, we found estrogen treatment increased Let-7b expression level, which could be reversed by either cyclin d1 knockdown or DICER1 knockdown." (PMID 29262559, 2017). "However, we think that this normalization procedure might have a major drawback because of the role of DICER1, a miRNA-preprocessing enzyme, in breast cancer." (PMID 22353773, 2012). "Therefore, we reason that the mean miRNA-expression levels can vary depending on DICER1 expression and that normalization relative to the mean miRNA-expression level might obscure between-sample differences, particularly in breast cancer." (PMID 22353773, 2012). "Of note, 14q LOH, which encompasses breast cancer genes such as SERPINA1 and DICER1, was highly enriched in HR−/HER2+ Nigerian women." (PMID 34836952, 2021). "In ER+ breast cancer, miR-129 inhibits estrogen receptor 1 (ESR1)-mediated NOTCH signaling in CSC-like cells by suppressing cyclin D1/DICER1 mediated let-7 maturation, leading to increased NUMB expression to repress NOTCH signaling activity." (PMID 34572067, 2021). "Further, differences in expression of DICER1, AGO and DROSHA, all crucial to miRNA biosynthesis, between breast cancer subtypes have been shown." (PMID 31581940, 2019). "Our research revealed the mechanisms through which miR-208a functioned in breast cancer and BrCSCs, and identified the miR-208a-SOX2/β-catenin-LIN28-let-7a-DICER1 regulatory feedback loop in regulations of stem cells renewal." (PMID 26460550, 2015). "Immunohistochemical (IHC) analysis further confirmed the downregulation of DICER1 protein expression in breast cancer tissues compared to normal breast tissues (P < 0.05)." (PMID 40666073, 2025). "Indeed, it has been shown that sex-steroids regulate the protein expression of DICER1, DROSHA, XPO5, and Argonaute (AGO) proteins in human breast cancer and endometrium." (PMID 33477993, 2021). "PICK1 inhibits the binding of DICER1 to Smad2/3 and the processing of pre-miR-615-3p to mature miR-615-3p in breast cancer cells, thus exerting a negative feedback loop." (PMID 32336285, 2020). "In turn, PICK1 inhibits the binding of DICER1 to Smad2/3 and the processing of pre-miR-615-3p to mature miR-615-3p in breast cancer cells, thus exerting a negative feedback loop." (PMID 32336285, 2020).
breast carcinoma (continued). "Together, our data suggest that PICK1 inhibits the binding of DICER1 to Smad2/3 and the processing of pre-miR-615-3p to mature miR-615-3p in breast cancer cells, thus exerting a negative feedback loop." (PMID 32336285, 2020). "In this study, we found that Dicer1 had the lowest expression in rat mammary cancer without treatment (G2)." (PMID 32458624, 2020). "Besides, AXIN2, PLAG1, GPC3, DICER1 are not connected with any breast cancer genes." (PMID 31760937, 2019).